PGK2 (phosphoglycerate kinase 2)
Description:
Catalyzes the reversible conversion of 1,3-diphosphoglycerate to 3-phosphoglycerate and plays a role in glycolysis and gluconeogenesis (By similarity). Essential for sperm motility and male fertility. Not required for the completion of spermatogenesis (By similarity).
Synonyms: PGKB; PGKPS; PGK-2; HEL-S-272; dJ417L20.2
Tractability: PROTAC: ubiquitination databases record sites on it; its protein half-life has been measured; a small molecule that binds it is known.
Gene: Protein-coding gene on chromosome 6 (49,785,660 to 49,787,285, reverse strand). Ensembl gene ENSG00000170950.
Subcellular location: Cytoplasm
Subcellular location (Human Protein Atlas): End piece; Mid piece; Principal piece
Pathways (Reactome):
Metabolism: Gluconeogenesis; Glycolysis
Gene Ontology:
Molecular function: protein binding; ADP binding; ATP binding; phosphoglycerate kinase activity
Biological process: gluconeogenesis; glycolytic process; phosphorylation; canonical glycolysis
Cellular component: extracellular exosome; nucleus; sperm fibrous sheath; cilium; cytoplasm
Genetic constraint (gnomAD): Loss-of-function variants: 6 observed, 6.11 expected, observed/expected ratio (o/e) 0.98, 90% interval 0.53 to 1.76. That is too few expected variants to judge how well the gene tolerates losing a copy. Missense variants: 580 observed, 528.95 expected, observed/expected ratio (o/e) 1.1, 90% interval 1.02 to 1.17. Synonymous variants: 207 observed, 190.3 expected, observed/expected ratio (o/e) 1.09, 90% interval 0.97 to 1.22.
Homologues: Orthologues: chimpanzee PGK2 (98% identical), pig PGK2 (89% identical), dog PGK2 (88% identical), rat Pgk2 (87% identical), macaque PGK2 (86% identical), mouse Pgk2 (86% identical), zebrafish pgk1 (82% identical), tropical clawed frog pgk1 (80% identical), Caenorhabditis elegans pgk-1 (69% identical), Drosophila melanogaster Pgk (68% identical), Drosophila melanogaster CG9961 (58% identical). Paralogues in human: PGK1 (87% identical).
Diseases named in the same sentence as PGK2 in open-access papers:
PGK2 is named in the same sentence as 19 diseases in open-access papers, as found by Europe PMC text mining. Sharing a sentence is not in itself a finding about the gene and the disease. The quoted sentences say what the papers report.
asthenozoospermia (4 papers, 2019 to 2025). "The lactylation level of PGK2, a key enzyme in glycolysis, were significantly reduced in asthenozoospermia." (PMID 41192556, 2025). "In the reproductive system, the examination of sperm in elderly and young male patients with asthenospermia showed that the level of Pgk2 was reduced." (PMID 31703718, 2019). "•Downstream products of PGK2 rescue motility defect in asthenozoospermia." (PMID 41192556, 2025).
Infertility (4 papers, 2015 to 2025). "Previous reports have shown that PGK2 expression not only significantly decreases in sperm of idiopathic asthenozoospermic patients, normozoospermic men consulting for infertility and normozoospermic men with IVF failure, but also declines in the tests and spermatozoa of elderly men." (PMID 40497989, 2025). "A number of mouse strains with KOs of sperm-specific metabolic enzymes (phosphoglycerate Kinase 2, glyceraldehyde 3-phosphate dehydrogenase, and lactate dehydrogenase C) display sperm motility defects which correlate to male-specific infertility, but in vivo migration has not been studied." (PMID 37152282, 2023). "This is consistent with the infertility or sub-fertility of Gapdhs−/−, Pgk2−/− and Eno4Gt/Gt knockout male mice, which lack testis-specific forms of the glycolytic enzymes glyceraldeyhde-3-phosphate dehydrogenase, phosphoglycerate kinase and enolase, respectively." (PMID 27103217, 2016). "For a subset of testis-specific candidates, i.e., TKTL1, LDHC, and PGK2, their germ cell expression was validated and it was demonstrated that such markers could be distinguished between semen from fertile and infertile men." (PMID 26097523, 2015).
breast carcinoma (2 papers, 2021). "We determined the expression of PGK1 and PGK2 in various human cancer types and found that it was significantly elevated in breast cancer vs. the normal tissue." (PMID 34291087, 2021). "PGK2 showed a significant expression-driven dependency (R = 0.65, FDR = 0.014) in breast cancer cell lines and was overexpressed in 7% of BRCA cases." (PMID 34552204, 2021).
colon cancer (2 papers, 2023 to 2024). "PGK2 is not only a key enzyme in the glycolysis pathway but can be secreted by a variety of tumor cell lines, including pancreatic, breast, and colon tumor cells." (PMID 39509399, 2024).
liver cancer (2 papers, 2023). An epithelial or non-epithelial malignant neoplasm that arises from the liver. "Esculetin (at a concentration of 50 mM) was effective against HepG2 liver cancer cells, by binding to three potential targets (phosphoglycerate kinase 2 (PGK2), glycerol-3-phosphate dehydrogenase (GPD2) and glucose-6-phosphate isomerase (GPI))." (PMID 37175299, 2023).
lung adenocarcinoma (2 papers, 2021 to 2023). A carcinoma that arises from the lung and is characterized by the presence of malignant glandular epithelial cells. "Although PGK2 is in the same family, it also showed consistent trends in the survival curve in lung cancer and lung adenocarcinoma patients." (PMID 34091600, 2021).
lung carcinoma (2 papers, 2021 to 2023). "Similarly, the RNA level from in-silico analyses with next-generation sequencing assays showed PGK1, rather than PGK2, overexpression in several malignant lung cancer cells." (PMID 34091600, 2021).
cryptorchidism (1 paper, 2017). The failure of one or both testes of a male fetus to descend from the abdomen into the scrotum during the late part of pregnancy. "And the Ptbp2 and Pgk2 mRNA levels were significantly decreased in parallel, leading us to conclude that the negative correlation between Ptbp2 levels and germ cell injury in unilateral cryptorchidism murine model." (PMID 29045475, 2017).
depression (1 paper, 2024). "Two (14%) of the 14 total disrupted glycolytic genes were downregulated: ENO4 and PGK2, and their expression was 2.4× lower in depression groups compared to control groups (LFC = −1.19)." (PMID 39125835, 2024).
glioma (1 paper, 2021). A benign or malignant brain and spinal cord tumor that arises from glial cells (astrocytes, oligodendrocytes, ependymal cells). "The result showed that P7C3 significantly reduced the protein expression level of PGK1 and PGK2, especially PGK1, in glioma cells, and the reduction in protein level was concentration-dependent." (PMID 34221965, 2021). "However, PGK2 mRNA levels were very low or even not expressed in gliomas." (PMID 34221965, 2021).
male infertility (1 paper, 2021). The inability of the male to effect fertilization of an ovum after a specified period of unprotected intercourse. "Previously knockout of such types of retrogenes, including Cetn1, Cstf2t, Pgk2 and Rpl10l, always resulted in spermatogenic abnormalities and male infertility." (PMID 34249105, 2021).
ovarian carcinoma (1 paper, 2009). A malignant neoplasm originating from the surface ovarian epithelium. "We tested for the expression of five of the known retrogenes, UTP14C, PGK2, RPL10L, RPL39L and UBL4B in normal human ovary and ovarian cancers." (PMID 19333399, 2009).
pancreatic ductal adenocarcinoma (1 paper, 2024). An infiltrating adenocarcinoma that arises from the epithelial cells of the pancreas. "The expression of PGK2 in serum was also significantly increased in patients with pancreatic ductal adenocarcinoma compared to the normal group." (PMID 39509399, 2024).
tumor (10 papers, 2019 to 2025). "Notably, simultaneous overexpression of several non-canonical glycolytic isoforms (HK2, HK3, HKDC1, ALDA, GAPDHS, and PGK2), previously linked to tumor development and progression, has been observed in patients with AUD." (PMID 41009047, 2025). "Of note, PGK2 is almost exclusively expressed in germ cells, whereas HK2 overexpression is considered a hallmark of tumor cells." (PMID 41009047, 2025). "In the case of PGK2, its overexpression has been reported in tumor tissues of patients with diverse types of adenocarcinomas, including hepatic, and is associated with a worse prognosis." (PMID 41009047, 2025). "In summary, our results suggest that isoscopoletin plays an anti-cancer role by regulating glycolysis-related proteins GPD2, GPI, Hsp90α and PGK2, and then inhibiting the glycolysis process and proliferation of tumor cells." (PMID 39509399, 2024). "Among them, GPD2, GPI, HSP90AA1 and PGK2 are involved in promoting glycolysis and tumor cell proliferation." (PMID 39509399, 2024). "Measurement of the target protein in tumor tissue showed an increase in PGK2, GPD2 and GPI in response to esculetin treatment." (PMID 37175299, 2023). "This can be partly explained by the high expression of PGK2, which enables the tumor cells to tolerate hypoxia and allows these cells to acquire compounds for synthesis and metabolism through the glycolysis pathway." (PMID 33692828, 2021). "Target protein measurement of the tumor tissue revealed an increase in PGK2, GPD2, and GPI in response to the esculetin treatment." (PMID 32292350, 2020). "PGK2 expression is regulated by oxygen tension, and its increased expression level often reflects faster tumor growth and stronger anaerobic growth habit." (PMID 32292350, 2020). "For example, in tumor tissues of patients with lung adenocarcinoma, high PGK2 expression shows worse prognosis of patients." (PMID 32292350, 2020). "To compare PGK1 and PGK2 mRNA levels between tumor and normal tissues, we analyzed the RNA-Seq data of 11,908 tumor cases with 1582 paired normal tissues across 34 cancer types from TCGA datasets." (PMID 31578148, 2019). "Glycolysis is accomplished through a series of enzymatic reactions in the cytoplasm, and the increased expression and activity of its associated enzymes are essential in tumor cells, among which GPD2, GPI, Hsp90α and PGK2 are involved in promoting glycolysis and cancer cell proliferation." (PMID 39509399, 2024). "Increased PGK2 expression reflects rapid tumor growth and increased growth in anaerobic conditions." (PMID 33692828, 2021). "In all types of cancer, the PGK1 mRNA levels in tumor and matched normal tissues were approximately 212 to 214 times higher than those of PGK2, which could hardly be detected." (PMID 31578148, 2019). "As well as in EESCC, cell cycle (e.g., PCM1, LIG1, etc.)and glycolysis (e.g., PGK2, ENO3, etc.)were predominant in the tumor tissues of EDAC." (PMID 35397555, 2022). "Many experiments show that the PGK2, GPD2), and GPI are key enzymes of glycolysis, and in promoting tumor cells play an important role in the process of glycolysis." (PMID 32292350, 2020). "This study suggests that isoscopoletin may exist an anti-tumor effect by regulating the glycolysis-related proteins GPD2, GPI, Hsp90α and PGK2, inhibiting the glycolysis process in HCC cells, then blocking the energy supply of tumor cells." (PMID 39509399, 2024). "The KEGG signaling pathway enrichment results also indicated that isoscopoletin might play an anti-tumor role by affecting the core targets of glycolysis pathway, such as GPD2, GPI, Hsp90AA1 and PGK2, which were the intersection of most glycolysis-related pathways." (PMID 39509399, 2024).
cancer (6 papers, 2019 to 2025). A tumor composed of atypical neoplastic, often pleomorphic cells that invade other tissues. "The drug may treat cancer by binding to PGK2, GPD2, and GPI and inhibit their energy metabolism and activity." (PMID 32292350, 2020). "Then, the anti-cancer effect may contain attenuating the conformational changes required for PGK2, GPD2, and GPI activation." (PMID 32292350, 2020). "Various metabolites produced during glycolysis, such as the PGK2 and GPI are involved in the synthesis of nucleic acids and fatty acids for cancer cells." (PMID 32292350, 2020). "When esculetin exhibits an anti-cancer effect, GPI, GPD2, and PGK2 with a higher degree were selected for the following experiments." (PMID 32292350, 2020). "Furthermore, differences were observed in the expression of several non-canonical and/or embryonic isoforms (HK3, HKDC1, ALDA, GADPH-S, PGK2, and PKM) between patients and controls, as well as in the expression of isoforms considered hallmarks of cancer, such as HK2." (PMID 41009047, 2025). "Pathways in cancer, central carbon metabolism in cancer, glycolysis/gluconeogenesis, and so on also suggested that isoscopoletin might affect the expression and activity of cancer-related proteins by binding to GPD2, GPI, Hsp90AA1 and PGK2." (PMID 39509399, 2024).
infection (1 paper, 2023). The state of being infected such as from the introduction of a foreign agent such as serum, vaccine, antigenic substance or organism. "Germ cell markers (PLZF for spermatogonia, PGK2 for spermatocytes, and PRM2 for spermatids) were not significantly modified by the infection at any time points." (PMID 37830818, 2023).
PGK2 also shares sentences with these, for which no sentence is quoted: Obesity (2 papers); adenocarcinoma (1); atherosclerosis (1).